MTOR (mechanistic target of rapamycin kinase)
Diseases named in the same sentence as MTOR in open-access papers (continued):
Sharing a sentence is not in itself a finding about the gene and the disease.
thyroid cancer (continued). "Thus, observed potent induction of ferroptosis, GPX4-dependent novel suppression of mTOR pathway and DNA damage repair response in preclinical in vitro model of TC supports GPX4 targeting for therapeutic benefit in advanced therapy-resistant thyroid cancers." (PMID 36371529, 2022). "In summary, although many complicated questions have not been answered, our study was the first to identify the mTOR/HIF1α/ENO1 pathway in thyroid carcinoma progression and ENO1 as a regulator of CST1, thereby paving the way for early diagnosis and efficient therapy of thyroid carcinoma." (PMID 33968941, 2021). "Whether and how pasireotide can potentiate everolimus, a clinically relevant mTOR inhibitor, in thyroid cancer of follicular epithelium origin has not been studied previously." (PMID 30807575, 2019). "In the present study, we examined the expression of HMGB1 in various thyroid cancer cell lines and patient samples, HMGB1 involvement in autophagy, its influence on NIS degradation and iodide uptake of thyroid cancer cells and its relationship with ROS/AMPK/mTOR pathway." (PMID 31331356, 2019). "In their study, curcumin was found to exert selective cytotoxicity on thyroid cancer cells but not normal epithelial cells and acted as an autophagy inducer through activation of MAPK while inhibition of mTOR pathways." (PMID 39906716, 2025). "Whilst in PDAC cell lines there was no change in proliferation, in uveal melanoma (UM) and Thyroid Cancer (TC) AHNAK2 upregulates the PI3K/AKT pathway, known to regulate mTOR and thereby controlling proliferation, growth and survival." (PMID 39849106, 2025). "Moreover, a phase II clinical trial proposed the combination of Temsirolimus (an mTOR inhibitor) and Sorafenib as a possible alternative in RAI-refractory thyroid cancer, especially in patients who received no prior treatment." (PMID 33292371, 2020).
pulmonary fibrosis (145 papers, 2011 to 2025). Chronic progressive interstitial lung disorder characterized by the replacement of the lung tissue by connective tissue, leading to progressive dyspnea, respiratory failure, or right heart failure. "The PI3K/Akt/mTOR axis is implicated in idiopathic pulmonary fibrosis (IPF), which is considered a risk factor for lung cancer." (PMID 37049920, 2023). "The activation of PI3K/Akt/mTOR pathway causes pulmonary fibrosis and lung injury by increasing lung fibroblasts and lung epithelial cells." (PMID 35165507, 2022). "TGF-β-induced activation of mammalian target of rapamycin (mTOR) activity has also been implicated in multiple fibrotic conditions, including idiopathic pulmonary fibrosis, chronic pancreatitis, and cancer-associated fibrosis." (PMID 35211358, 2022). "Endoplasmic reticulum (ER) stress is also implicated in the development of lung fibrosis via the activation of PI3K/AKT/mTOR-dependent signaling." (PMID 29518028, 2018). "The administration of Everolimus (EVE), a mTOR inhibitor used in transplantation and cancer, is often associated with adverse effects including pulmonary fibrosis." (PMID 29677166, 2018). "Alterations in mTOR signaling are closely associated with dysregulation of autophagy, inflammation, and cell growth and survival, leading to the development of lung fibrosis." (PMID 29518028, 2018). "Rapamycin and mTOR-siRNA can inhibit the mTOR signaling pathway, protecting premature rats from lung injury caused by high oxygen and having a certain inhibitory effect on lung fibrosis." (PMID 38886743, 2024). "The rs1476792 SNP was also validated in ADs and is associated to RPS6KB2 (ribosomal protein), previously implicated in idiopathic pulmonary fibrosis and lung radiotoxicity via regulation of the mTOR signaling pathway and was dysregulated in World Trade Center responders with associated sarcoidosis." (PMID 38390497, 2023). "The potential application of mTOR inhibitors for pulmonary fibrosis was discouraged by a clinical study that showed everolimus, another mTOR inhibitor other than rapamycin, was associated with more rapid disease progression in patients with surgical lung biopsy-confirmed IPF." (PMID 26382847, 2015). "Furthermore, mTOR signaling is closely associated with the dysregulation of autophagy, inflammation, as well as cell growth and survival, resulting in the development of pulmonary fibrosis." (PMID 37755300, 2023). "In addition, mTOR appears to be associated with cell proliferation and lung fibrosis." (PMID 33693011, 2021). "Suppression of PI3K/AKT/mTOR signaling alleviated pulmonary fibrosis in the BLM-induced animal model." (PMID 41007776, 2025). "Evidence shows that upregulation of the PI3K/AKT signaling pathway can activate the autophagy regulator mTOR, inhibit autophagy, and exacerbate endothelial cell apoptosis, thereby promoting pulmonary fibrosis." (PMID 40365538, 2025). "The AKT pathway is involved in pulmonary fibrosis by regulating its downstream, such as mTOR, HIF-1α, and the FOX family." (PMID 40743122, 2025). "This study by Nakashima and colleagues reveals that systemic miR-26a deficiency reduces pulmonary fibrosis by upregulating PTEN, thereby suppressing TIMP-1 in the PI3K/Akt-mTOR pathway." (PMID 41323794, 2025). "For example, inhibition of the miR-34a-mediated SIRT1/mTOR signaling pathway attenuates D-gal-induced senescence in rat brain tissue, and alveolar epithelial cell dysfunction is alleviated in aged miR-34a−/− pulmonary fibrosis mice." (PMID 40110129, 2025). "NOB inhibits amiodarone-induced pulmonary fibrosis by inhibiting the TGF-β3-related PI3K/AKT/mTOR cascade, inhibiting alpha smooth muscle actin (α-SMA) expression and hindering collagen deposition." (PMID 40660593, 2025). "Systemic miR-26a KO enhances PTEN expression and suppresses the fibrosis-promoting molecule TIMP-1 by inhibiting the PI3K/Akt-mTOR pathway, thereby attenuating pulmonary fibrosis, as summarized in graphical abstract." (PMID 41323794, 2025).
pulmonary fibrosis (continued). "Recent studies also found exogenous HMGB1 participated in the epithelial-mesenchymal transition via the PI3K/Akt/mTOR pathway in pulmonary fibrosis." (PMID 38469295, 2024). "Through the suppression of the PI3K/Akt/mTOR pathway, aspirin activates autophagy, thereby promoting pulmonary fibrosis." (PMID 39220589, 2024). "Further, LncRNA TUG1 promotes the idiopathic pulmonary fibrosis progression of interstitial lung disease via activating the PI3K/Akt/mTOR pathway." (PMID 38582846, 2024). "The overactivation of mTOR in alveolar epithelial cells and impaired lung autophagy are related to the pathogenesis of lung fibrosis." (PMID 38886743, 2024). "Excessive activation of mTOR is observed in the bleomycin-induced mouse model of lung fibrosis, contributing to the formation of pulmonary fibrosis." (PMID 38886743, 2024). "Dysregulation of mTOR signaling in the lungs results in different pathologies, such as idiopathic pulmonary fibrosis, COPD, pulmonary hypertension, lymphangioleiomyomatosis and other lung cancers." (PMID 38802925, 2024). "In lung fibrosis, the mTOR signaling pathway is involved in the regulation of myofibroblast apoptosis." (PMID 38886743, 2024). "The modulation of mTOR, either inhibition or enhancement, can be utilized for the treatment of lung fibrosis." (PMID 38886743, 2024). "Eupatilin ameliorates lung fibrosis by activating the Sestrin2/PI3K/Akt/mTOR-dependent autophagy pathway." (PMID 39544928, 2024). "TGF‐β‐induced PI3K/AKT/mTOR activation has been widely reported in multiple degenerative disorders, including idiopathic pulmonary fibrosis (IPF), cardiac and renal fibrosis." (PMID 36869852, 2023). "The activation of Akt is facilitated through the regulation of its downstream proteins, such as GSK-3β, mTOR, HIF-1α, and NF-κB, which are implicated in the pathogenesis of pulmonary fibrosis." (PMID 37781713, 2023). "The IPA showed enrichment in pulmonary fibrosis-relevant pathways, including mTOR, VEGF, PDGF, and B-cell receptor signaling." (PMID 37344825, 2023). "This study is the first to show that the effect of AMI in pulmonary fibrosis is at least partially achieved through inhibition of the PI3K/Akt/mTOR signaling pathway." (PMID 37380638, 2023). "Mechanistically, HMGB1 activated the PI3K/AKT/mTOR signaling pathway to increase cell proliferation and migration, promoting endothelial-mesenchymal transition in pulmonary fibrosis." (PMID 37945340, 2023). "PI3K/AKT can promote pulmonary fibrosis by regulating its downstreams such as mammalian target of rapamycin (mTOR), hypoxia inducible factor-1a (HIF-1a)." (PMID 36865908, 2023). "Our findings elucidate the mechanism of the pro-autophagic and anti-fibrotic effects of miR-29a-3p in silicosis and indicate that the miR-29a-3p/Akt3/mTOR axis plays a crucial role in silica-induced lung fibrosis." (PMID 37511199, 2023). "PI3K/Akt/mTOR pathway plays a key regulatory role in promoting fibroblast activation and autophagy inhibition in lung fibrosis." (PMID 36651446, 2023). "In IPF, after TF binding to CD71, the PI3K/AKT/mTOR/PTEN pathway is activated, which increases TGF‐β expression and causes pulmonary fibrosis." (PMID 38018577, 2023). "We have demonstrated that Duvelisib attenuated pulmonary fibrosis through inhibiting the phosphorylation of PI3K/AKT/mTOR signal pathway in vitro." (PMID 36651446, 2023). "PI3K/Akt/mTOR is a classic autophagy signalling pathway, and studies have shown that the PI3K/Akt/mTOR signalling pathway is closely related to pulmonary fibrosis." (PMID 36651446, 2023). "This study focused on investigating the therapeutic efficacy of nintedanib in bleomycin-mediated pulmonary fibrosis (PF) mice through PI3K/Akt/mTOR pathway." (PMID 37160579, 2023). "With the inhibition of mTOR, autophagosomes can be formed to carry out autophagy, hence presenting the anti-fibrotic effects of celastrol on pulmonary fibrosis." (PMID 37772226, 2023).
pulmonary fibrosis (continued). "The results confirmed that nintedanib can alleviate pulmonary fibrosis by regulating the PI3K/Akt/mTOR signaling pathway." (PMID 37160579, 2023). "Herein, these findings indicate that THSG inhibits the TGF-β1-induced Akt/mTOR pathway in human lung fibroblasts and alveolar epithelial cells, thereby leading to autophagy activation and subsequent alleviating lung fibrosis." (PMID 36267283, 2022). "Our previous study reported that deletion of miR-301a protected mice from bleomycin-induced lung fibrosis by reducing mTOR activation in a Tsc1-dependent manner." (PMID 35211358, 2022). "We have demonstrated that SDC2-mediated CD148 activation inhibits experimental lung fibrosis by regulating PI3K/Akt/mammalian target of rapamycin (mTOR) signaling, thereby increasing autophagy and decreasing levels of p62 and subsequent NF-κB inactivation." (PMID 35181688, 2022). "SiRT-1/AKT/mTOR pathway is implied in numerous fibrotic conditions, as liver, cardiac, kidney, and pulmonary fibrosis." (PMID 36301384, 2022). "TGF-β signaling can activate Akt in a SEMA 7A-dependent manner, which in turn activates downstream mTOR signaling and promotes lung fibrosis." (PMID 35721111, 2022). "Relevant evidence suggests that mTOR inhibition effectively inhibits the fibrosis process in both experimental models of radiation‐ and bleomycin‐induced pulmonary fibrosis." (PMID 35959254, 2022). "Lung fibrosis is alleviated by inhibition of the PI3K/Akt/mTOR signaling pathway in the BLM-induced pulmonary fibrosis animal model." (PMID 36267283, 2022). "Pharmacological targeting of the mTOR pathway by small-molecule inhibitors such as rapamycin was shown to alleviate experimental pulmonary fibrosis." (PMID 36430565, 2022). "Some studies have shown that the activation of PI3K/Akt/mTOR signal pathway can promote the occurrence and development of pulmonary fibrosis." (PMID 35886594, 2022). "Here, our study unveiled that EG treatment not only decreased oxidative stress but also inhibited EMT during PM2.5-induced lung fibrosis by blocking the activation of AKT/mTOR pathway." (PMID 35707275, 2022). "Our previous study demonstrated that ablation of miR-301a in mice protected against bleomycin-induced lung fibrosis through the Tsc1/mTOR axis signaling pathway." (PMID 35211358, 2022). "IL-17A-producing T cells exacerbate fine particulate matter–induced pulmonary fibrosis by inhibiting PI3K/Akt/mTOR-mediated autophagy." (PMID 36105212, 2022). "RNA-seq also demonstrated that Gyps inhibited the mTOR and c-Myc signaling in pulmonary fibrosis mice, which was further validated by Western blot and immunohistochemistry." (PMID 35095515, 2021). "In this review, we discuss the current literature regarding the therapeutic potential of mTOR-Is in kidney transplant recipients with COVID-19 with a focus on pulmonary fibrosis." (PMID 34497515, 2021). "Recently, a study showed that reduction of miRNA-126 drove lung fibrosis by activating the PI3K/AKT/mTOR pathway after carbon black treatment." (PMID 34256802, 2021). "Recent data indicate that the agent can suppress lung fibrosis by autophagy activation, partially due to the transmission of Rheb/mTOR/p70S6K signals, as demonstrated in fibroblasts of mice with bleomycin-induced (BLM) lung fibrosis." (PMID 34451904, 2021). "Each has been shown to be involved in fibroblast biology in the context of pulmonary fibrosis, with mTOR representing a potential target for antifibrotic therapy." (PMID 33561015, 2021). "These protective effects of TET on pulmonary fibrosis are associated with activation of autophagy through promoting NRF2-SQSTM1 axis and Rheb-mTOR signaling." (PMID 34880752, 2021). "Conversely, a potent PI3K/mTOR inhibitor showed anti-fibrotic activity in idiopathic pulmonary fibrosis." (PMID 34943039, 2021).
pulmonary fibrosis (continued). "Intriguingly, our previous research also found compromised autophagy in mice with an aberrant activation of mTOR in alveolar epithelial cells, which had the potential to develop into more severe pulmonary fibrosis." (PMID 34395518, 2021). "Studies have shown that the PI3K/AKT/mTOR pathway is closely related to macrophage activation as well as glycolysis in pulmonary fibrosis." (PMID 34900687, 2021). "In conclusion, Gyps exerted anti-pulmonary fibrosis activity by inhibiting the AKT/mTOR/c-Myc pathway." (PMID 35095515, 2021). "Another study revealed that lung fibroblasts displayed augmented aerobic glycolysis through activation of the PI3K-Akt-mTOR/PFKFB3 pathway in LPS-induced pulmonary fibrosis." (PMID 34603058, 2021). "In the present study, we demonstrated that Gyps markedly inhibited the AKT/mTOR/c-Myc pathway in pulmonary fibrosis." (PMID 35095515, 2021). "In pulmonary fibrosis, the inhibition of mTOR with rapamycin alone has been shown to reduce collagen formation." (PMID 34304701, 2021). "In an idiopathic pulmonary fibrosis model, mammalian target of rapamycin/peroxisome proliferator-activated receptor-γ complex 1α/β (mTOR/PGC-1α/β) axis is markedly upregulated in senescent lung epithelial cells." (PMID 32215170, 2020). "The activation of PI3K/Akt/mTOR pathway is involved in pulmonary fibrosis and lung injury by regulating lung fibroblasts and lung epithelial cells." (PMID 33140889, 2020). "Our new signals of association with IPF susceptibility provide increasedsupport for the importance of mTOR signaling in pulmonary fibrosis as well as thepossible implication of mitotic spindle-assembly genes." (PMID 31710517, 2020). "Altogether, mediated by mTOR activity, aging influenced the response of lung fibroblasts to autophagy and enhanced the vulnerability to lung fibrosis." (PMID 32724454, 2020). "The observation that decreased DEPTOR expression associateswith increased susceptibility to IPF supports recent studies demonstratingthe importance of mTOR signaling in lung fibrosis." (PMID 31710517, 2020). "The present study next confirmed that inhibiting the expression of TSC1 in miR-301a−/− mice significantly activated mTOR and promoted pulmonary fibrosis." (PMID 32585629, 2020). "The inhibition of miR-301a has been shown to reduce mTOR activation and collagen contents using the bleomycin murine model of pulmonary fibrosis." (PMID 32585629, 2020). "The results demonstrated that the miR-301a/TSC1/mTOR axis was a key positive regulator of fibrogenesis, providing a new target for the clinical treatment of pulmonary fibrosis." (PMID 32585629, 2020). "The findings also revealed a significant role for the miR-301a/TSC1/mTOR axis in pulmonary fibrosis." (PMID 32585629, 2020). "The increase in ROS by PQ increased mTOR activity, inhibited autophagy and exacerbated PQ-induced pulmonary fibrosis." (PMID 30744607, 2019). "Abnormal mTOR pathway activation is essential in fibrotic diseases because mTOR signalling largely governs pulmonary fibrosis." (PMID 30744607, 2019). "Ligustrazin blocked PQ-induced PI3K/Akt/mTOR and Hh signalling by increasing miR-193a expression, thereby attenuating PQ-induced lung fibrosis." (PMID 30744607, 2019). "Long-term PQ exposure blocked miR-193a expression, reduced PI3K/Akt/mTOR signalling, increased oxidative stress, inhibited autophagy, increased Hh signalling, and facilitated the formation of pulmonary fibrosis." (PMID 30744607, 2019). "The phosphoinositide 3-kinase (PI3K)/protein kinase B (AKT)/mammalian target of rapamycin (mTOR)-dependent pathway is dysregulated in fibroproliferative diseases, like pulmonary fibrosis." (PMID 30704051, 2019). "Ligustrazin blocked PI3K/Akt/mTOR and Hh signalling as well as reduced oxidative stress via increasing miR-193a expression and autophagy, all of which reduced pulmonary fibrosis." (PMID 30744607, 2019).